IL6 (interleukin 6)
Diseases named in the same sentence as IL6 in open-access papers (continued):
Sharing a sentence is not in itself a finding about the gene and the disease.
female infertility (3 papers, 2023 to 2025). Diminished or absent ability of a female to achieve conception. "Based on our bioinformatic and experimental findings, we propose a working model for the pathophysiology of female infertility centered on the crosstalk between IL-6, miRNAs, autophagy, and ubiquitination." (PMID 41227338, 2025). "Network modeling further elucidated the collaborative roles of IL6 and miRNAs in female infertility." (PMID 41227338, 2025). "Current research on female infertility primarily examines isolated pathways, neglecting the integrative roles of IL-6, miRNAs, autophagy, and ubiquitination." (PMID 41227338, 2025). "This study hypothesizes that IL-6-driven inflammation, miRNA dysregulation, and impaired autophagy–ubiquitination networks synergistically contribute to female infertility." (PMID 41227338, 2025). "This study explores how the cytokine IL-6, the autophagy marker LC3, ubiquitination process, and three miRNAs, miR-146a-5p, miR-9-5p, and miR-9-3p, contribute to the control of ovarian function and female infertility." (PMID 41227338, 2025). "In this study, we employed a comprehensive bioinformatics approach and experimental analysis to unravel the molecular crosstalk between interleukin-6 (IL6), autophagy, ubiquitination, and three microRNAs, miR-146a-5p, miR-9-3p, and miR-9-5p, in the context of female infertility." (PMID 41227338, 2025).
Fibroadenoma (3 papers, 2017 to 2024). A benign tumor of the breast characterized by the presence of stromal and epithelial elements. "In addition, in the group with fibroadenomas, the lowest level compared to HER2(+)/(−) and control groups was shown for such cytokines as IL-6 (2.78 pg/mL), IL-8 (55.73 pg/mL), and IL-18 (62.5 pg/mL)." (PMID 39456554, 2024).
focal epilepsy (3 papers, 2015 to 2023). A seizure caused by a localized disorder. "In drug-resistant focal epilepsy, especially in TLE, the association of proinflammatory cytokines, particularly interleukin-6 (IL-6), with epileptic disease profiles has been well established." (PMID 37025699, 2023).
Fulminant hepatic failure (3 papers, 2016 to 2017). Hepatic failure refers to the inability of the liver to perform its normal synthetic and metabolic functions, which can result in coagulopathy and alteration in the mental status of a previously healthy individual. "IL‐6 is elevated in patients with fulminant hepatic failure and involved in both hepatocyte regeneration and in T‐cell activation and differentiation." (PMID 28213967, 2017).
gastric adenoma (3 papers, 2013 to 2024). A neoplastic polyp that arises from the stomach. "The expression of VEGF and IL-6 has been found up-regulated in gastric adenomas." (PMID 39507201, 2024). "In this model, gastric adenomas spontaneously and reproducibly develop with 100% penetrance in 4‐week‐old mice with an absolute genetic dependence on bi‐allelic expression of the il11rα and Stat3 genes, but completely independent of IL6 signaling." (PMID 30885958, 2019).
gastrointestinal mucositis (3 papers, 2014 to 2022). "However, TLR4 knockout mice completely lack an IL-6 response, and IL-6 may be a more promising therapeutic target for preventing or alleviating chemotherapy-induced gastrointestinal mucositis." (PMID 35719331, 2022).
HELLP syndrome (3 papers, 2022 to 2025). A life-threatening condition that can potentially complicate pregnancy. "A recent systematic review shows evidence that sFlt-1, PlGF, IL-6, IL-6/IL-10 ratios are interesting candidate biomarkers for cardiovascular risk stratification after PE or HELLP syndrome (hemolysis, elevated liver enzymes and low platelets)." (PMID 35883900, 2022).
hemarthrosis (3 papers, 2020 to 2025). Bleeding into the joints. "During the acute phase (day 3), all M1 markers were elevated in response to hemarthrosis (Il6, Il1β, Nos2, Cxcl2 and Il1r1), whereby Il6 and Nos2 were suppressed to baseline levels by rhFVIII and mFcFVIII alike, without effects on Il1β, Cxcl2 and Il1r1." (PMID 40388523, 2025). "IL-1β, IL-6, and MCP1 are involved in inflammation and progression of hemarthrosis in HA mouse models, while in vitro studies utilizing human cartilage cultures have indicated that IL-1β blockade is more effective than TNFα blockade in reducing damage following exposure to blood." (PMID 32595650, 2020).
hemoglobinopathies (3 papers, 2020 to 2024). "Thus, our results suggest that chemokines CXCL10 and CCL2 and cytokines, TNF-α, IL-8, and IL-6 may contribute to the overall pro-inflammatory response and could be utilized for predicting the severity of Plasmodium infection or a hemoglobinopathy." (PMID 33424841, 2020).
hepatocellular adenoma (3 papers, 2015 to 2023). A benign epithelial neoplasm arising from the hepatocytes. "It has been reported that excess IL-6 production is closely associated with cancer cachexia and inflammation hepatocellular adenoma." (PMID 28430601, 2017). "Given that inflammatory hepatocellular adenoma is characterized by the activation of the IL-6/JAK/STAT pathway, we suspect that this efficacy may be associated with the suppression of IL-6." (PMID 36724021, 2023).
herpes simplex infection (3 papers, 2018 to 2025). "In line with this, herpes simplex infection in neonates is known to trigger vast amounts of IL-6 and inadequate amounts of IL-12 and IFN-α, resulting in a Th2 dominated immune response." (PMID 40677723, 2025).
Hip dysplasia (3 papers, 2016 to 2022). The presence of developmental dysplasia of the hip. "On the other hand, elevated levels of IL-6 seem to predict progression in joint contracture, short stature, and hip dysplasia." (PMID 36611367, 2022). "Inflammatory cytokines are high in MPS I. IL‐6 and PYD were associated with progression in joint contracture, short stature, and hip dysplasia over time." (PMID 33728251, 2021). "Third, we identified PYD as a prognostic biomarker of future growth and hip dysplasia and IL‐6 of future rate of change in joint ROM." (PMID 33728251, 2021). "As expected, low TNF-α, IL-1β and IL-6 expression levels were obtained in normal hip dysplasia tissues and in tissues after mechanical loosening." (PMID 26004143, 2016). "In addition, IL-6 and PYD levels appear to be associated with progression in joint contracture, short stature, and hip dysplasia." (PMID 36611367, 2022).
hookworm infection (3 papers, 2011 to 2022). "In CCs, Ascaris lumbricoides or Schistosoma mansoni infections were associated with an impaired Th1-type response (IFN-gamma, IL-6 and TNF-alpha) in PBMCs mainly with SEB stimulations, whereas in TB patients only hookworm infection showed a similar pattern." (PMID 35976976, 2022). "Compared to Helm-/TB, hookworm infection also showed significantly lower production of IL-6 in unstimulated (p<0.05) and PPD stimulated (p<0.05) PBMCs." (PMID 35976976, 2022). "Thus, the suppression of IL-6 could also impact the APPR as this cytokine mediates increasing levels of protein electrophoretic fractions as observed in younger canine pups with hookworm infection." (PMID 35529837, 2022). "In unstimulated PBMC cultures from negative, nonendemic individuals lower concentrations of inflammatory IL-1β, IL-6, and TNF-α were detected when compared with participants with hookworm infection." (PMID 21772981, 2011). "Additionally, immunological differences between animals from high- and low-intensity hookworm seasons, as well as ivermectin-treated animals, indicate hookworm infection modulation of the host immune response, as evidenced by a lower IL-6 mRNA expression in the non-treated groups." (PMID 35529837, 2022).
Hypernatremia (3 papers, 2020 to 2022). An abnormally increased sodium concentration in the blood. "Thus far, only a few studies have discussed the relationship of hypernatremia with IL-6 and IL-10." (PMID 36140385, 2022).
hyperprolactinemia (3 papers, 2019 to 2024). Abnormally high level of prolactin in the blood. "Finally, HY7801 reduced the expression of genes encoding inflammatory cytokines (i.e., Tnf and Il-6), cyclooxygenase-2 (Cox-2), and inducible nitric oxide synthase (iNOS) in mice with hyperprolactinemia." (PMID 39599674, 2024). "The link between hyperprolactinemia and high IL-6 levels in neuropsychiatric lupus patients suggests that there is a reciprocal interaction between the neuroendocrine and immune systems." (PMID 37864188, 2023).
hypertensive heart disease (3 papers, 2020 to 2024). Abnormal enlargement of the heart resulting from long-standing hypertension. "Hypertensive heart disease rats treated with AS-IV (40 mg/kg) or fosinopril had significantly down-regulated IL-6 and TNF-α expression levels compared with the LN group." (PMID 34803698, 2021). "The role of IL‐6 signalling in hypertensive heart disease and its sequelae is controversial." (PMID 32164044, 2020). "The findings of the PPI network indicated that IL-6, TNF, IL-1β, and NFKBIA were predicted as the main genes of AS-IV against hypertensive heart disease and the KEGG pathways analysis showed that TNF signaling pathway was its key pathway." (PMID 34803698, 2021). "Our findings indicated that the targeted genes of AS-IV against hypertensive heart disease are involved in oxidative stress and inflammation, including SOD2, SOD1, IL-6, TNF, and IL-1β." (PMID 34803698, 2021).
Hypoinsulinemia (3 papers, 2023 to 2025). A decreased concentration of insulin in the blood. "Plasma concentration of glucose was normal despite the hypoinsulinemia, and plasma concentrations of pro- and anti-inflammatory IL-6 and IL-10 were, respectively, higher in the SL group compared to C (P<0.05)." (PMID 38808884, 2024).
hypovitaminosis (3 papers, 2019 to 2022). "Moreover, due to retrospective character of the study we did not investigate mineral and vitamin deficiencies, neither measured concentration of interleukin-6." (PMID 35682209, 2022).
idiopathic dilated cardiomyopathy (3 papers, 2016 to 2022). Decreased function of the heart associated with cardiac enlargement and congestive heart failure, of unknown cause. "Clinical data have demonstrated that idiopathic dilated cardiomyopathy patients with higher serum IL-6 have a lower ejection fraction and worse prognosis." (PMID 35402550, 2022).
idiopathic inflammatory myopathies (3 papers, 2023 to 2025). "IL-6, IL-15, and IL-18 have been noted to be elevated systemically in patients with idiopathic inflammatory myopathies (IIM)." (PMID 41488665, 2025). "In recent decades, several pieces of evidence have drawn greater attention to the topic of innate immunity, in particular, interferon (IFN) and Interleukin 6 in the pathogenesis of idiopathic inflammatory myopathies (IIM)." (PMID 36993798, 2023).
infantile hemangioma (3 papers, 2019 to 2023). "It has been reported that STAT3 was highly activated in proliferating infantile hemangioma, and IL-6/STAT3 pathway play a pivotal role in tumorigenesis and progression of multiple cancer types." (PMID 36167680, 2022). "Moreover, expression levels of other proangiogenic factors, such as matrix metalloproteinase 1 and interleukin-6 were also were found to be suppressed in HemSCs after corticosteroid treatment, indicating that HemSCs were the potential target for infantile hemangioma treatment." (PMID 30713220, 2019).
influenza A (H1N1) (3 papers, 2012 to 2022). Viral infectious disease caused by the H1N1 strain of the influenza type A virus. "The inflammatory cytokine IL-6 has been implicated in both seasonal and severe pandemic H1N1 influenza A (H1N1pdm) infection." (PMID 22679491, 2012). "The present study also reported the lack of association between SNPs in the IL6, IFNG, IL17A, and TGFB genes and disease severity of Influenza A(H1N1)pdm09 virus infection." (PMID 34946862, 2021). "Since IL-6 is nonspecifically upregulated in all type of infections, it cannot be used as a biomarker of influenza A(H1N1)pdm09 virus infection but can be used as a biomarker to predict fatal outcomes in subjects with confirmed influenza A(H1N1)pdm09 virus infection." (PMID 34946862, 2021).
intestinal parasite infections (3 papers, 2018 to 2023). "Here, intestinal parasite infections (IPIs) and blood filariasis were associated with decreased Th1 (IL-6) and Treg (IL-10) responses." (PMID 35421083, 2022).
Intussusception (3 papers, 2020 to 2025). An abnormality of the intestine in which part of the intestine invaginates (telescopes) into another part of the intestine. "Levels of serum cytokines on admission, including interleukin (IL) 2, IL-4, IL-6, tumor necrosis factor α (TFN-α), and interferon γ (IFN-γ) were rarely increased, except that 1 critically ill patient with underlying intussusception had an IL-6 level of 3868.86 pg/mL." (PMID 32492165, 2020).
ischemic optic neuropathy (3 papers, 2013 to 2021). "However, overactivated microglia provide excessive amounts of the inflammatory ligands IL-6, IL-1β, and TNF-α, causing ROS, iNOS, NFκB, and NLRP3 inflammatory complex activation; additionally, disruption of neuronal homeostasis was observed in ischemic optic neuropathy." (PMID 34573098, 2021). "In both ischemic optic neuropathy and IOP elevation animal models, alterations of LIF, IL-6 and other JAK-STAT signaling pathway components in the optic nerve have been reported." (PMID 23383263, 2013). "Finally, anterior ischemic optic neuropathy (AION) has been reported in a patient receiving TCZ, but the incidence of GCA-related visual manifestations during disease flare in patients receiving IL-6 blockade therapy is unknown." (PMID 33407817, 2021).
Klebsiella Infections (3 papers, 2012 to 2023). Infections with bacteria of the genus KLEBSIELLA. "Mast cell-derived IL-6 has been implicated in the promotion of survival in Klebsiella infection." (PMID 37138882, 2023). "Previous studies revealed that TRIF- and MyD88-dependent TLR signaling, which stimulate proinflammatory cytokines TNF-alpha and IL-6, contribute to host defense against Klebsiella infection." (PMID 22427976, 2012). "Several pro-inflammatory cytokines including IL-6, IL-1β, and TNF-α were also decreased after astragaloside IV treatment, indicating that astragaloside IV could inhibit inflammation-related apoptosis caused by Klebsiella infection by inhibiting TGF-β1 signaling pathway." (PMID 37493767, 2023).
Klebsiella pneumonia (3 papers, 2013 to 2021). An pneumonia caused by infection with Klebsiella. "As for clinical samples, three cytokines including IL‐6, IL‐12p70, and G‐CSF showed significant differences between infection group (Staphylococcus aureus and Klebsiella pneumonia group) and negative control group." (PMID 34725873, 2021).
laryngeal tumors (3 papers, 2015 to 2024). "Among these, Interleukin (IL)-6 (P ═ 0.021) was highly expressed in laryngeal tumors, and the expression levels of IL-1β (P ═ 0.008), IL-6 (P ═ 0.005), and IL-8 (P ═ 0.05) were higher in patients with poorly differentiated laryngeal tumors." (PMID 38920620, 2024). "Using CSC from a different cancer source, we found that silencing IL-6 gene expression with siRNA significantly enhanced the cisplatin effect in laryngeal tumor cells as indicated by reductions in cell proliferation, colony formation, invasion, and an increase in the number of apoptotic cells." (PMID 28878571, 2017).
legionellosis (3 papers, 2017 to 2024). Any disease caused by Legionella bacteria. "Furthermore, following Legionella infection, IL-6 and TNF-α were evidently reduced in the supernatant of transfected macrophages with anti-Lpg2936 siRNA, while control-transfected macrophages showed a marked increase of both cytokines in a time-dependent manner." (PMID 32064256, 2019).
Leigh syndrome (3 papers, 2020 to 2024). A progressive neurological disease defined by specific neuropathological features associating brainstem and basal ganglia lesions. "To investigate the role of microglia in the pathogenesis of Leigh syndrome, we partially ablated microglia using Pexidartinib and demonstrated improved survival, in association with attenuation of IL6 increase in LS mice." (PMID 36741056, 2022). "Our findings suggest that not only there are increased numbers and activation of microglia in Leigh syndrome patients, but LS neurons are also more susceptible to proinflammatory cytokines like IL6." (PMID 36741056, 2022). "Here, we provide evidence that, based on the measurements we have employed, chronic neuroinflammation induced by continuous IL-6 overexpression does not substantially impact the phenotype of a well-established Leigh Syndrome model." (PMID 38212783, 2024).
liver abscesses (3 papers, 2018 to 2025). "The results for expression levels of TNF-α, IL-6 and IL-1β in tissue at the edge of liver abscesses were similar to the immunohistochemistry data." (PMID 29420539, 2018).
lung neoplasm (3 papers, 2017 to 2021). A benign or malignant, primary or metastatic neoplasm involving the lungs. "It has been reported that serum IL-6 levels in NSCLC patients (especially metastatic cases) are higher than healthy subjects, and blockade of IL-6/STAT3 signalling results in the inhibition of lung tumour growth." (PMID 29062084, 2017).
macrosomia (3 papers, 2021 to 2024). "Probiotics also reduced the level of inflammatory markers (high-sensitivity C-reactive protein, interleukin-6, tumor necrosis factor-α, and malondialdehyde), incidence of macrosomia, and newborn hospitalization." (PMID 34578921, 2021). "An intervention of low GI advice had no impact on levels of CRP in women with a high risk of GDM nor on IL-6 and TNF-α in women at high risk for macrosomia in the second half pregnancy." (PMID 33806342, 2021).
major depressive episode (3 papers, 2015 to 2025). "For instance, studies on patients experiencing major depressive episodes have demonstrated a positive correlation between the severity of depressive symptoms, IL-6 concentrations, and cortisol levels." (PMID 40141696, 2025).
Malignant hyperthermia (3 papers, 2016 to 2020). Malignant hyperthermia is characterized by a rapid increase in temperature to 39-42 degrees C. Malignant hyperthermia may occur in response to either inhalational anesthetics such as halothane, to muscle relaxants such as succinylcholine, or to exercise. "IL-6 and TNFα levels have also been found to be significantly increased in NMS, as has IL-6 in malignant hyperthermia (MH)." (PMID 27411542, 2016).
meconium aspiration syndrome (3 papers, 2008 to 2020). A serious condition in which a newborn breathes a mixture of meconium (the first intestinal discharge) and amniotic fluid into the lungs around the time of delivery. "The pro-inflammatory cytokines IL-6 and TNFα are secreted to the tracheal aspirate fluid of infants with meconium aspiration syndrome." (PMID 25885541, 2015).
meningococcal meningitis (3 papers, 1993 to 2015). "We examined the compartmentalization of bioactive tumour necrosis factor (TNF) and interleukin 6 (IL-6) to the subarachnoid space and systemic circulation in patients with meningococcal meningitis and septic shock/bacteraemia." (PMID 18475498, 1993). "However, the severity of meningococcal meningitis is directly correlated with the production of IL-1β, TNF-α, IL-6 and IL-8." (PMID 26316174, 2015).
mesenchymal tumors (3 papers, 2020 to 2025). "This hypothesis is indirectly confirmed by the observation that Myc signaling is upregulated in proneural GBM tumors, while mesenchymal tumors exploit pathways related to inflammatory response and IL6/JAK/STAT372." (PMID 39773984, 2025). "circPOK interacts with ILF2/3 complex to promote Il6 transcription in mesenchymal tumors." (PMID 36747292, 2023).